ZNF837 (zinc finger protein 837)
Description:
May be involved in transcriptional regulation.
Tractability: No criterion of Open Targets' tractability assessment is met for any kind of drug.
Gene: Protein-coding gene on chromosome 19 (58,367,614 to 58,381,054, reverse strand). Ensembl gene ENSG00000152475.
Subcellular location: Nucleus
Subcellular location (Human Protein Atlas): Nucleoli
Gene Ontology:
Molecular function: identical protein binding; protein binding; DNA-binding transcription factor activity, RNA polymerase II-specific; RNA polymerase II cis-regulatory region sequence-specific DNA binding
Biological process: regulation of transcription by RNA polymerase II
Cellular component: nucleus
Genetic constraint (gnomAD): Missense variants: 953 observed, 608.78 expected, observed/expected ratio (o/e) 1.57, 90% interval 1.48 to 1.65. Synonymous variants: 473 observed, 289.17 expected, observed/expected ratio (o/e) 1.64, 90% interval 1.52 to 1.76.
Homologues: Orthologues: macaque ZNF837 (91% identical), tropical clawed frog zfx (17% identical), mouse Zfy1 (16% identical), mouse Zfy2 (16% identical), zebrafish zfx (16% identical), rat Zfy1 (15% identical). Paralogues in human: ZNF304 (33% identical), ZNF256 (33% identical), ZNF792 (32% identical), ZSCAN2 (32% identical), ZNF418 (32% identical), ZNF551 (31% identical), ZNF583 (31% identical), ZSCAN20 (31% identical), ZNF587B (31% identical), ZNF79 (30% identical), ZNF480 (30% identical), ZNF548 (29% identical), and 26 more.